RN7SKP96 (RN7SK pseudogene 96)
Gene: Miscellaneous RNA gene on chromosome 4 (86,336,318 to 86,336,614, reverse strand). Ensembl gene ENSG00000252757.
Homologues: Orthologues: mouse Gm55016 (39% identical). Paralogues in human: 7SK (56% identical), RN7SKP48 (56% identical), RN7SKP178 (56% identical), RN7SKP227 (54% identical), RN7SKP174 (53% identical), RN7SKP118 (53% identical), RN7SKP62 (53% identical), RN7SKP156 (52% identical), RN7SKP187 (52% identical), RN7SKP292 (52% identical), RN7SKP38 (52% identical), RN7SKP146 (52% identical), and 284 more.